ALX1 (ALX homeobox 1)
Description:
Sequence-specific DNA-binding transcription factor that binds palindromic sequences within promoters and may activate or repress the transcription of a subset of genes. Most probably regulates the expression of genes involved in the development of mesenchyme-derived craniofacial structures. Early on in development, it plays a role in forebrain mesenchyme survival. May also induce epithelial to mesenchymal transition (EMT) through the expression of SNAI1.
Synonyms: CART1; FND3; HEL23
Tractability: No criterion of Open Targets' tractability assessment is met for any kind of drug.
Gene: Protein-coding gene on chromosome 12 (85,280,220 to 85,301,784, forward strand). Ensembl gene ENSG00000180318.
Subcellular location: Nucleus
Subcellular location (Human Protein Atlas): Nuclear bodies; Golgi apparatus; Nucleoplasm
Gene Ontology:
Molecular function: DNA-binding transcription activator activity, RNA polymerase II-specific; protein binding; RNA polymerase II transcription regulatory region sequence-specific DNA binding; sequence-specific double-stranded DNA binding; DNA-binding transcription factor activity, RNA polymerase II-specific; DNA binding; DNA-binding transcription factor activity; sequence-specific DNA binding
Biological process: negative regulation of transcription by RNA polymerase II; positive regulation of DNA-templated transcription; positive regulation of epithelial to mesenchymal transition; positive regulation of transcription by RNA polymerase II; embryonic skeletal system morphogenesis; negative regulation of DNA-templated transcription; neuron development; regulation of DNA-templated transcription
Cellular component: nuclear body; nucleoplasm; nucleus; chromatin; transcription regulator complex
Genetic constraint (gnomAD): Loss-of-function variants: 19 observed, 33.28 expected, observed/expected ratio (o/e) 0.57, 90% interval 0.4 to 0.84. The upper end of that interval is the gene's LOEUF score, 0.84, which puts it in group 3 of 6, group 1 being the genes least tolerant of losing a copy. Missense variants: 415 observed, 431.33 expected, observed/expected ratio (o/e) 0.96, 90% interval 0.89 to 1.04. Synonymous variants: 153 observed, 159.89 expected, observed/expected ratio (o/e) 0.96, 90% interval 0.84 to 1.09.
Gene-disease validity (ClinGen):
ClinGen rates the evidence that ALX1 causes each of these diseases.
frontonasal dysplasia - severe microphthalmia - severe facial clefting syndrome (autosomal recessive): Definitive.
Homologues: Orthologues: chimpanzee ALX1 (100% identical), rabbit ALX1 (98% identical), pig ALX1 (98% identical), mouse Alx1 (97% identical), rat Alx1 (96% identical), dog ALX1 (95% identical), guinea pig ALX1 (90% identical), tropical clawed frog alx1 (83% identical), zebrafish alx1 (70% identical). Paralogues in human: ALX4 (42% identical), ALX3 (39% identical), ARX (27% identical), VSX2 (24% identical), PITX2 (23% identical), RAX (22% identical), SHOX2 (22% identical), DMBX1 (22% identical), OTP (22% identical), PHOX2B (21% identical), PITX1 (21% identical), PRRX1 (21% identical), and 38 more.
Diseases named in the same sentence as ALX1 in open-access papers:
ALX1 is named in the same sentence as 46 diseases in open-access papers, as found by Europe PMC text mining. Sharing a sentence is not in itself a finding about the gene and the disease. The quoted sentences say what the papers report.
frontonasal dysplasia (9 papers, 2019 to 2026). A group of rare bone development disorders characterized by an array of abnormalities affecting the eyes, forehead, and nose, and linked to midfacial dysraphia. "FND3, which is the most severe phenotype of frontonasal dysplasia, is caused by loss of the ALX1 gene, which results in complete failure of fusion of the frontonasal process and the maxillary arch." (PMID 38673496, 2024). "In humans, ALX1 mutations are linked to severe frontonasal dysplasia (FND) and extreme microphthalmia, and ALX3 and ALX4 genes are associated with a phenotypic spectrum of hypertelorism and nasal-tip duplications." (PMID 35142342, 2022). "Variants of the transcription factor ALX1 are implicated in the development of Frontonasal Dysplasia." (PMID 32914578, 2020). "Previous knockout studies have shown that Alx1 is required for normal craniofacial mesenchyme migration as it relates to frontonasal dysplasia." (PMID 41010016, 2025). "Mutations in genes encoding the ALX homeodomain-containing transcription factors (ALX1, ALX3 and ALX4) are associated with frontonasal dysplasia and produce midfacial phenotypes in vertebrate species." (PMID 38063857, 2024). "In mouse embryos, Alx1, Alx2, and Alx3 are expressed in NCCs in the frontonasal process, something that highlights their connection to frontonasal dysplasia, while in zebrafish, alx1 is present in migrating NCCs during the first stages of migration." (PMID 38673496, 2024). "Frontonasal dysplasia resulted from ALX1, ALX3, ALX4 can also present bifid nose." (PMID 38097983, 2023). "ALX1 mutations in humans are linked to severe congenital anomalies of the facial skeleton (frontonasal dysplasia, FND) with malformation or absence of eyes and orbital contents (micro- and anophthalmia)." (PMID 35142342, 2022). "Given the spectrum of human midfacial anomalies associated with disrupted functions of TFAP2A (branchio-oculo-facial syndrome), TFAP2B (Char syndrome), and ALX1, ALX3 and ALX4 (frontonasal dysplasia), these findings link features of previously disparate disorders into a shared genetic hierarchy." (PMID 38063857, 2024).
microphthalmia (4 papers, 2011 to 2026). Congenital or developmental anomaly in which the eyeballs are abnormally small. "Loss of ALX1 function causes the frontonasal dysplasia syndrome FND3, characterized by severe facial clefting and microphthalmia." (PMID 35127681, 2022). "Disruption of ALX1 causes severe facial clefting and microphthalmia in FND3 patients, whereas loss of function mutations in ALX3 and ALX4 underlie the milder FND1 and FND2 syndromes, respectively." (PMID 35127681, 2022). "In humans, mutations of ALX1 result in frontonasal dysplasia and eye abnormalities including microphthalmia and anophthalmia." (PMID 33182738, 2020). "Disruption of the ALX1 gene was recently reported to cause an autosomal recessive microphthalmia and a severe facial cleft." (PMID 21595979, 2011). "Loss of ALX1 gene function causes severe facial clefting and extreme microphthalmia." (PMID 41670220, 2026). "Correspondingly, knockout of alx1 in zebrafish also causes microphthalmia and coloboma." (PMID 33182738, 2020).
ovarian carcinoma (3 papers, 2021 to 2025). A malignant neoplasm originating from the surface ovarian epithelium. "For instance, the methylation level of homeobox transcription factor ALX1, influenced by the CpG site cg02409351, can induce Snail expression to promote epithelial-to-mesenchymal transition and invasion of ovarian cancer cells." (PMID 40177272, 2025). "ALX1 promotes migration and invasion by upregulating Snail expression in lung and ovarian cancer cells." (PMID 36690674, 2023). "ALX1 knockdown suppresses cell invasion and tumor formation due to attenuated ALX1/Snail axis in lung and ovarian cancer cells, or Wnt/beta-catenin signaling pathway in melanoma cells." (PMID 36690674, 2023).
Brachycephaly (2 papers, 2021 to 2024). An abnormality of skull shape characterized by a decreased anterior-posterior diameter. "The ALX1 gene in Burmese cats disrupts the cranial morphogenesis and causes brachycephaly in the heterozygous state." (PMID 38540427, 2024). "In the current study, we genotyped Cornish Rex cats, cats of other breeds, and F1 hybrids between Cornish Rex and domestic cats for the deletion in the LPAR6 gene associated with the rex phenotype and deletion in the ALX1 gene, a candidate for brachycephaly." (PMID 38540427, 2024). "Bioinformatic analysis of 63K Cat DNA Array data revealed selection signature on the FCA B4 in the region, where ALX1 gene, which was identified as a causal locus for brachycephaly in Burmese cats, is situated." (PMID 38540427, 2024). "The extreme brachycephaly in Burmese cats is at least partly due to a 12 bp deletion in the ALX1 gene encoding the ALX homeobox 1 protein (OMIA 001551-9685)." (PMID 34946872, 2021).
facial cleft (2 papers, 2014 to 2022). A congenital abnormality consisting of an opening or gap in the face, which results from incomplete fusion of one or more of the embryonic facial prominences. "Since some studies believed that the occurrence of the facial cleft was related to some genes related to craniofacial malformation such as IRF6, ALX1, ALX3, and ADH1C." (PMID 36090555, 2022).
lung carcinoma (2 papers, 2021 to 2023). "HNF1A, ALX1, AR, and GR play certain roles in lung cancer development and progression, and/or they have been associated with the overall survival." (PMID 36832225, 2023).
chondrosarcoma (1 paper, 2011). A malignant cartilaginous matrix-producing mesenchymal neoplasm arising from the bone and soft tissue. "In their study, the authors isolated two additional isoforms of the Alx1 that were generated by alternative splicing from rat chondrosarcoma." (PMID 21595979, 2011).
craniosynostosis (1 paper, 2023). Craniosynostosis is defined as the premature fusion of one or more cranial sutures leading to secondary distortion of skull shape resulting in skull deformities with a variable presentation. "Though ALX4 was not differentially expressed between cases and controls in our study, ALX1 was significantly increased in metopic craniosynostosis in our primary and male-stratified models." (PMID 36982425, 2023). "ALX1 has not previously been associated with craniosynostosis, however, it is involved in osteogenesis and regulates a lncRNA transcript that is involved in bone marrow mesenchymal cell osteogenesis." (PMID 36982425, 2023).
ductal carcinoma (1 paper, 2011). "Mcs6 human orthologous transcripts that have been reported as differentially expressed between non-diseased breast tissue and ductal carcinoma tissue encode for two phosphatases (DUSP6, PPP1R12A), a proteoglycan (EPYC), a redox regulator (TXNRD1), and two uncharacterized proteins (ALX1, ZDHHC17)." (PMID 21625632, 2011).
endometrial carcinoma (1 paper, 2021). A malignant tumor arising from the epithelium that lines the cavity of the uterine body. "In this study, we demonstrated that miR-192-5p is downregulated through promoter hypermethylation and functions as a powerful tumor suppressive microRNA by targeting ALX1 in endometrial carcinoma." (PMID 34104082, 2021).
frontofacionasal dysplasia (1 paper, 2011). Fronto-facio-nasal dysostosis is characterized by multiple craniofacial anomalies (brachycephaly, blepharophimosis, ptosis, S-shaped palpebral fissures, coloboma, cleft lip and palate, deformed nostrils, encephalocele, hypertelorism, midface hypoplasia, malformed eyes, and absent inner eyelashes). "The clinical symptoms caused by the loss-of-function mutations of the ALX1 gene were related to the clinical spectrum of frontofacionasal dysplasia caused by the two other ALX genes, ALX3 and ALX4." (PMID 21595979, 2011).
meningoencephalocele (1 paper, 2020). A congenital abnormality in which the meninges protrude through a defect in the cranium. "A familial craniofacial malformation with meningoencephalocele has been recognized in Burmese cats, which is caused by ALX Homeobox 1 (ALX1) variant." (PMID 32575532, 2020).
metastatic disease (1 paper, 2026). "Collectively, our findings identify lnc-ALX1-2:10 as a novel lncRNA that promotes aggressive phenotypes in PCa, highlighting its potential as a therapeutic target for metastatic disease." (PMID 41775788, 2026).
neuroblastoma (1 paper, 2011). Neuroblastoma (NB) is the most common solid, extracranial childhood tumor. "To assess the influence of the translocation on ALX1 gene expression, we next conducted a reporter gene assay in Chinese ovary hamster (CHO) cells and a SKNSH neuroblastoma cell line." (PMID 21595979, 2011).
non-small cell lung carcinoma (1 paper, 2016). A group of at least three distinct histological types of lung cancer, including non-small cell squamous cell carcinoma, adenocarcinoma, and large cell carcinoma. "In addition, Esteller and the associates used methylation array to establish methylation profiles of stage I Caucasian non-small cell lung cancer and identified that methylation of two or more genes in HIST1H4F, PCDHGB6, NPBWR1, ALX1, and HOXA9 correlated with an increased risk of cancer recurrence." (PMID 27484806, 2016).
NUT carcinoma (1 paper, 2023). "We further show that the BRD4-NUT/p300 chromatin condensation is important for transcriptional activation of pro-proliferation genes such as ALX1, a highly expressed oncogene in NUT carcinoma cells, and resulting ALX1/Snail signaling and epithelial-to-mesenchymal transition." (PMID 36690674, 2023).
ptosis (1 paper, 2022). The drooping of the upper eyelid. "A mutation altering the splice acceptor of the fourth exon of ALX1 has been associated with a milder form of FND3, with patients displaying ptosis (droopy upper eyelid), broad nasal root, short and wide nasal bridge, bifid or depressed nasal tip and anteverted nares." (PMID 35127681, 2022).
spina bifida (1 paper, 2010). A congenital neural tube defect in which vertebrae are not fully formed. "The purpose of this study is to evaluate the potential association between variations among human CITED2, CREBBP, EP300, TFAP2A, CARM1 and ALX1 genes and the risk for spina bifida." (PMID 20932315, 2010). "We have observed modest associations with risk of spina bifida in CITED2, EP300, CREBBP, TFAP2A and CARM1 genes but not ALX1 gene." (PMID 20932315, 2010).
cancer (6 papers, 2013 to 2023). A tumor composed of atypical neoplastic, often pleomorphic cells that invade other tissues. "ALX1 is a homeodomain-containing transcription factor, and recently implicated as a regulator of Snail expression in activating cancer invasion and migration." (PMID 36690674, 2023). "It has been reported that ALX1 is associated with increased epithelial-to-mesenchymal transition (EMT) in cancer progression." (PMID 36690674, 2023). "Some genes, which appeared to be virtually switched off in B4GALNT2-expressing cells, are involved in the basic properties of cancer cells, such as stemness (SOX2, ROR1), epithelial to mesenchymal transition (EMT) (NID1, ALX1), and growth (FAM110B, PEG10, MID2)." (PMID 32290493, 2020).
tumor (5 papers, 2021 to 2026). "Using these three specially designed EC cell lines (ie: miR-192-NC, miR-192, miR-192+ALX1), we demonstrated that ectopic expression of ALX1 significantly abrogated the tumor-suppressive effect induced by miR-192-5p." (PMID 34104082, 2021). "In our study, ALX1 overexpression promoted tumor progression in EC at least partly through upregulation of MMP2, MMP9, VEGF and vimentin." (PMID 34104082, 2021). "Taken together, these data indicate that miR-192-5p mediates tumor suppressive effect through ALX1 in EC." (PMID 34104082, 2021). "ALX1 was verified as a direct target of miR-192-5p and demonstrated to mediate the tumor-suppressive function of miR-192-5p." (PMID 34104082, 2021). "miR-192-5p is silenced by promoter hypermethylation, which lead to the overexpression of ALX1 and promotion of tumor progression in EC." (PMID 34104082, 2021). "ALX1 plays a key role in tumor progression and metastasis, and it has been shown to regulate the expression of genes that induce epithelial to mesenchymal transition in primary mesenchymal cells." (PMID 34012960, 2021).
neurological diseases (1 paper, 2014). "Homozygous deletion of CEP290 (OMIM*610142) and ALX1 (OMIM*601527) in this region are associated with different neurological diseases, but our case is a gain of copy number." (PMID 24926319, 2014).
ALX1 also shares sentences with these, for which no sentence is quoted: Anophthalmia (2 papers); breast carcinoma (2); dysplasia (2); melanoma (2); Branchio-oculo-facial syndrome (1); Char syndrome (1); cleft lip (1); cleidocranial dysplasia (1); cognitive decline (1); cousin syndrome (1); Endove syndrome (1); eyelid coloboma (1); gastric cancer (1); Intellectual disability (1); kidney cancer (1); leiomyoma (1); liver carcinoma (1); lung disease (1); microcephaly (1); Mowat-Wilson syndrome (1); neurodevelopmental disorder (1); osteosarcoma (1); prostate carcinoma (1); Sagittal craniosynostosis (1); Umbilical hernia (1).